TP63 (tumor protein p63)
Diseases named in the same sentence as TP63 in open-access papers (continued):
Sharing a sentence is not in itself a finding about the gene and the disease.
breast cancer (60 papers, 2011 to 2025). A primary or metastatic malignant neoplasm involving the breast. "It is in this context that this study aimed to investigate the probable involvement of the SNP rs17506395 of the TP63 gene and the CCR5Δ32 mutation in the occurrence of breast cancer in Burkina Faso." (PMID 38585642, 2024). "The aim of this study was to investigate the probable involvement of polymorphisms rs17506395 in the TP63 (tumour protein 63) gene and the CCR5Δ32 mutation in the occurrence of breast cancer in Burkina Faso." (PMID 38585642, 2024). "The SNP rs17506395 (T > G) (189803530T > G,189521319T > G,211785T > G) of the TP63 gene, which was initially associated with fertility, has also been implicated in the development of several cancers, including breast cancer." (PMID 38585642, 2024). "The following analysis demonstrated that TP63 as an autophagy-related gene is a low-risk factor for the prognosis of breast cancer, that is, the lower the expression of TP63, the worse the prognosis of breast cancer." (PMID 35480110, 2022). "We successfully constructed a prognostic risk model of breast cancer and screened out an autophagy-related prognostic gene -TP63." (PMID 35480110, 2022). "Based on bioinformatics analysis, this study first constructed a prognostic risk model successfully and screened the prognostic gene TP63 as one of the autophagy-related genes (ARGs) in breast cancer." (PMID 35480110, 2022). "At the genetic level, a functional SNP rs17506395 (T>G) located in the TP63 gene, which was initially associated with fertility has recently been associated with several cancers including breast cancer in Asian populations." (PMID 32856845, 2020). "The polymorphism at SNP rs17506395 locus of TP63 was investigated on 111 breast cancer patients and 224 controls belonging to three ethno-linguistic groups." (PMID 32856845, 2020). "In conclusion, results of this study revealed an association between polymorphism at SNP rs15706395 of TP63 gene and the risk of developing breast cancer among Cameroonian women of 40 years and less." (PMID 32856845, 2020). "The TP63 gene is associated with breast cancer resistance to cis-diammine-dichloroplatinum II (cisplatin), a particular drug used for the treatment of solid tumors and aggressiveness." (PMID 30641908, 2019). "It was found that IL-1β was able to upregulate the chemoresistance-associated gene, the tumor protein 63 (TP63) isoform ∆NP63α, contributing to the acquisition of cisplatin resistance in breast cancer cells." (PMID 31492049, 2019). "This evidence is further supported by the Kaplan-Meier survival plotting analysis which indicated that high levels of STAT6 and TP63 expression were associated with longer DMFS of patients with breast cancer." (PMID 26208975, 2015). "In addition to these polymorphisms and mutations, the SNP rs17506395 (TP63 gene) and the CCR5Δ32 mutation are thought to be involved in the development of breast cancer." (PMID 38585642, 2024). "It was suggested that the T allele, which is mostly observed in breast cancer patients, may enhance the expression of TP63 gene." (PMID 32856845, 2020). "Although the mechanism associating the presence of T allele at SNP rs17506395 with breast cancer is not yet understood, this allele seems to be able to alter the regulator power of TP63 gene, which could contribute to breast cancer development." (PMID 32856845, 2020). "If we assume that, it is likely that the high frequency of T allele among young patients may promote high expression of TP63, which in tune drive the aggressiveness of basal-like breast cancer." (PMID 32856845, 2020). "Although rare mutations of the TP63 gene have been reported in human tumors, multiple studies have reported undetectable or very low expression of this isoform, in different human neoplasia, including invasive and metastatic lesions of mammary carcinoma." (PMID 31159154, 2019).
breast cancer (continued). "TP63 is often implicated in epithelial cell cancers such as squamous cell carcinoma (SCC), lung, and breast cancer." (PMID 39791744, 2025). "Clinical analyses reveal that TP63 and FOXO3a expression are significantly reduced in breast cancer tissues compared to normal tissues, whereas ATF6 and GRP78 expression are elevated." (PMID 40223122, 2025). "In the GEPIA database, TP63 gene expression was significantly lower in breast cancer tissues, including basal-like, HER2-positive, luminal A and luminal B subtypes, compared to normal tissues." (PMID 40223122, 2025). "Correlation heatmap analysis and protein-protein interaction (PPI) network demonstrated strong associations among TNFSF4, TP63, CD24, ESR1, and PRLR, suggesting their potential roles in HR+ breast cancer progression." (PMID 40612672, 2025). "In the literature, to our knowledge, no other study in the past has shown a probable link between the genotypes of the rs17506395 polymorphisms of the TP63 gene and the Δ32 mutation of the CCR5 gene and breast cancer." (PMID 38585642, 2024). "Intracellular accumulation of NBR1 is also involved in prometastatic differentiation; it induces aggressive basal differentiation through the expression of cytokeratin 14 and TP63 in breast cancer." (PMID 36831154, 2023). "Intracellular accumulation of NBR1 is also involved in prometastatic differentiation that induces aggressive basal differentiation such as cytokeratin 14 and TP63 in breast cancer." (PMID 36831154, 2023). "According to the different clinicopathological characteristics in the Kaplan-Meier Plotter database, the relationship between TP63 and the prognosis in breast cancer was explored." (PMID 35480110, 2022). "In the future, we need to further explore about how autophagy and apoptosis regulating the tumor microenvironment via the TGF-β1/TP63 signaling pathway in breast cancer." (PMID 35480110, 2022). "A decline in TP63 expression was related to shorter survival times of patients with breast cancer, bladder cancer, and lung cancer." (PMID 36936274, 2022). "TGF-β1 can promote autophagy and inhibit apoptosis on MDA-MB-231 and MCF-7 breast cancer cells by targeting TP63 to affect the occurrence and development of breast cancer." (PMID 35480110, 2022). "Compared with a human mammary epithelial cell line MCF-10A, the expression levels of GSDMC, GZMB and IL18 were upregulated, while TP63 was found with lower expression level in breast cancer cells SK-BR-3, BT-549, MCF-7, and MDA-MB-231 using RT-qPCR assay." (PMID 36936274, 2022). "We explored that the prognostic value of TP63 in breast cancer by the Kaplan-Meier Plotter database." (PMID 35480110, 2022). "We explored the interaction and effects between TGF-β1 and TP63 in breast cancer on autophagy and apoptosis." (PMID 35480110, 2022). "In summary, our study constructed a prognostic model related to autophagy in breast cancer, and TP63 was screened out as a key factor in the prognostic model." (PMID 35480110, 2022). "Our study demonstrated that the molecular mechanism of TGF-β/TP63 signaling in regulating autophagy and apoptosis of breast cancer and provided a potential prognostic marker in breast cancer." (PMID 35480110, 2022). "In order to illuminate the correlation between TGF-β1 and TP63, we detected the expression level of TP63 in breast cancer cells with TGF-β1 induced." (PMID 35480110, 2022). "TP63 increases expression of epidermal growth factor receptor in breast cancer and increases the response of breast cancer to cisplatin." (PMID 35060926, 2022). "Using univariate Cox regression analysis, a total of 4 autophagy-related genes (EIF4EBP1, IFNG, NRG1, TP63) were significantly correlated with overall survival (OS) of breast cancer." (PMID 35480110, 2022). "The results showed that the expression level of TP63 in breast cancer was positively correlated with the overall survival (OS) of patients [HR=0.41 (0.23-0.72), p=0.0013]." (PMID 35480110, 2022).
breast cancer (continued). "As shown, compared with MCF-10A, the expression levels of GSDMC, GZMB and IL18 were upregulated, while TP63 was found with lower expression level in breast cancer cells SK-BR-3, BT-549, MCF-7, and MDA-MB-231 (P < 0.05)." (PMID 36936274, 2022). "The clinical significance of TP63 in breast cancer was evaluated by analyzing the correlation between the expression of TP63 and clinical parameters." (PMID 35480110, 2022). "For example, TP63 was lowly expressed in breast cancer (BRCA) and highly expressed in lung squamous cell carcinoma (LUSC)." (PMID 35795676, 2022). "According to both the TCGA and GEO cohorts, a decrease of TP63 level was an indicator for poor survival status for breast cancer patients." (PMID 36936274, 2022). "Genetic predispositions to BC development in African population is poorly studied, and meanwhile the SNP rs17506395 in TP63 gene locus has been associated with the development of breast cancer in Asian women, no investigation has been undertaken within African population." (PMID 32856845, 2020). "By silencing TP63 expression, breast cancer cells acquired increasing resistance to cisplatin, suggesting its role in drug reaction." (PMID 32010179, 2019). "The role of the TP63 gene in breast cancer has been historically complicated by the fact that its gene codifies for two main isoforms, TAp63 and ΔNp63, having opposite functions." (PMID 31159154, 2019). "Analysis of 237 proteins as part of the Cancer Proteome Atlas revealed Tp63 which stimulates expression of sonic hedgehog pathway genes in mammary cancer stem cells was enriched in high TrkB-T1 expresser SCCs." (PMID 31221127, 2019). "Our previous RNA-seq analysis of IL-1β-stimulated 6D breast cancer cells showed increased expression of TP63, a gene classified in the group of drug-resistance-related genes." (PMID 30641908, 2019). "We have shown that TRPS1 reduced the metastatic ability of breast cancer cells by involving decommission of TP63 enhancer and repressing ΔNp63 expression." (PMID 30563971, 2018). "For example, the expression of ΔNp63 was suppressed by TRPS1-CHD4/NuRD(MTA2), which decommissioned TP63 enhancer leading to reduced metastatic ability of breast cancer cells and better survival of breast cancer patients." (PMID 30563971, 2018). "We recently reported results of CRISPR/Cas9-mediated TP63 knock-out in the HCC1806 basal-A breast cancer cell line." (PMID 27724925, 2016). "Because decreased TP63 levels have been associated with enhanced invasion and migration as well as metastatic potential of cancer cells, we hypothesized that, upon IL13Rα2 knockdown, IL-13 signaling suppresses metastasis by impairing the ability of breast cancer cells to migrate." (PMID 26208975, 2015). "Consistent with the role of TP63 as a suppressor of breast cancer cell migration, the combination of IL13Rα2 depletion concomitant with IL-13 treatment potently suppressed the migratory potential of metastatic MIV cells." (PMID 26208975, 2015). "Moreover, low TP63 and high GRP78 expression are associated with a poor prognosis in breast cancer patients." (PMID 40223122, 2025). "More isoform-specific studies need to be performed to confirm this hypothesis and resolve the discrepancies in the role of TP63 in breast cancer." (PMID 39791744, 2025). "Additionally, IL13Ralpha2 deletion upregulated TP63 and significantly reduced metastasis of breast cancer cells to the lungs, suggesting that TP63 acts as a tumor-suppressor gene and prevents metastasis in BLBC." (PMID 39791744, 2025).
breast cancer (continued). "With regard to the family history of breast cancer and age at diagnosis, no risk was found between these factors and the genotypes of the rs17506395 polymorphisms of the TP63 gene and the CCR5Δ32 mutation." (PMID 38585642, 2024). "Neither the (TG) genotype of the TP63 gene nor the (WT/Δ32) genotype of the CCR5 gene was associated with the development of breast cancer in our study population." (PMID 38585642, 2024). "Therefore, the effects of TGF-β1 and TP63 on autophagy and apoptosis in breast cancer cells were explored in this study." (PMID 35480110, 2022). "It is obvious that TGF-β1 enhanced the autophagy level in breast cancer cells by inhibiting TP63." (PMID 35480110, 2022). "Clarifying the importance of TGF-β1 and TP63 in breast cancer cells may provide a theoretical basis and a new idea for breast cancer treatment in the future." (PMID 35480110, 2022). "Similarly, TGF-β1 was determined to inhibit apoptosis of breast cancer cells by targeting TP63 from the WB results." (PMID 35480110, 2022). "High expression of miR-144 and TP63 was found to be correlated with significantly better overall survival in breast cancer and bladder carcinoma, suggesting that miR-144 expression might have prognostic value for several human cancers." (PMID 35459267, 2022). "It was disclosed that IL-1β could enhance the tumor protein 63 (TP63) isoform ΔNP63α, a chemoresistance-associated gene, adding to the cisplatin acquired resistance in breast cancer cells." (PMID 36119049, 2022). "The decreased expression of TP63 might have potential relation to hypomethylation, and predicted a poor OS rate for breast cancer patients." (PMID 36936274, 2022). "In breast cancer, TP63 induced the expression of GSDME via binding a specific site in GSDME." (PMID 36389801, 2022). "We clearly observed that TGF-β1 inhibits TP63 in breast cancer cells." (PMID 35480110, 2022). "Additionally, TGF-β1 promoted autophagy and inhibited apoptosis of breast cancer cells by inhibiting the expression of TP63." (PMID 35480110, 2022). "Our data provide mechanistic insights into how TRPS1 functions as a transcription repressor elucidating a new molecular mechanism underlying the transcription regulation of TP63 and providing a link between TRPS1 and migration and invasion of breast cancer cells." (PMID 30563971, 2018). "Importantly, the decrease in the ability of breast cancer cells to migrate was inversely proportional to TP63 expression levels, consistent with the role of TP63 as a suppressor of cell migration and metastasis." (PMID 26208975, 2015). "Moreover, low TP63 expression (p = 0.0012), high ATF6 expression (p = 0.0055) and high GRP78 expression (p = 0.0014) were significantly associated with poor prognosis in breast cancer patients." (PMID 40223122, 2025). "None of the polymorphisms rs17506395 of the TP63 gene (OR = 1.47, 95% CI = 0.69–3.17, P = 0.284) and the CCR5Δ32 mutation (OR = 1.32, 95% CI = 0.46–3.77; P = 0.79) were associated with the occurrence of breast cancer in this study." (PMID 38585642, 2024). "Genetic alterations in the TP63 (GenBank: NC_000003.12, ID: 8626) and CCR5 (receptor 5 chemokine co-receptor) (GenBank: NC_000003.12, ID: 1234) genes may increase the risk of developing breast cancer." (PMID 38585642, 2024). "Moreover, KRT15, MIA, and TP63 levels significantly decreased in breast cancer cells." (PMID 37842046, 2023). "In addition, a comparison between N0 and N1-N3 status of breast cancer patients demonstrated that cases with lymph-node metastasis had lower TP63 mRNA expression (P = 0.017), which might be due to its hypomethylation." (PMID 36936274, 2022). "In breast cancer, high expression of TP63 coupled with STAT6 has been shown to be associated with longer metastasis-free survival, indicating that TP63 could be involved in inhibiting the migration of breast cancer cells." (PMID 32010179, 2019). "However, transcriptional regulation of TP63 in breast cancer is still not fully understood." (PMID 30563971, 2018).
breast cancer (continued). "ZNF750 was recently described as an EMT repressor in breast cancer, an activity shared by OVOL2, TP63, and FOXO1." (PMID 38066300, 2023). "Studies have found that TP63 is a downstream effector of the TGF-β pathway and plays an important role in primary breast cancer." (PMID 35480110, 2022). "TP63 c.1127G>A (p.R376H) was identified in a female patient diagnosed with CRC and breast cancer at 56 and 59 years of age, respectively." (PMID 35158968, 2022). "The results indicated that EMC2, G6PD, FLT3, IFNG, ANO6, and SLC1A4 were positively correlated with ferroptosis while CISD1, TP63, and BRD4 were negatively correlated with ferroptosis in breast cancer." (PMID 34222241, 2021). "KRT14-expressing breast cancer cells were shown to lead the collective invasion process and to activate a basal gene program, which included TP63 and KRT5, needed for the initial phases of metastasis in breast cancer cells." (PMID 35187501, 2021). "We found that MYH11, TP63 and ELF5 were downregulated in breast cancer tissues, which is consistent with previous findings highlighting TP63 and ELF5 as tumor suppressors." (PMID 33216733, 2020). "As the malignancy of breast cancer increased, the expression of several ARGs, such as EIF4EBP1, FOS and TP63, decreased or increased." (PMID 33194339, 2020). "We identified networks regulated by known cancer drivers such as GATA3 and FOXA1 (breast cancer), SOX17 and FOXA2 (endometrial cancer), and NFE2L2, SOX2, and TP63 (squamous cell lung cancer)." (PMID 25994056, 2015). "These genes include TP63 for bladder cancer, FGFR2 and MAP3K1 for breast cancer, HNF1B for ovarian cancer, KLK3 for prostate cancer, and CDKN2A for skin cancer." (PMID 26374197, 2015). "Our study demonstrated that decreased TP63 expression is a negative and independent prognostic factor in breast cancer, and the TAp63 mRNA level was down-regulated in MDA-MB-231, HCC1954, and MCF-7 cells in laboratory tests, consistent with previous reports." (PMID 37842046, 2023). "Our data suggest that TP63, YWHAZ, BRCA1, CCND2, YWHAG, and HIPK2 can be potential genetic markers of prognostic assessment, immune infiltration and chemotherapeutic drug sensitivity in breast cancer patients." (PMID 36673982, 2023). "Furthermore, it is known that TP63 regulation via PI3K/Akt and immune response markers promote drug resistance in breast cancer." (PMID 33092068, 2020). "Moreover, targeting the decoy interleukin-13 receptor alpha 2 (IL13Ra2) upregulates the metastasis suppressor TP63 in an IL13-mediated, STAT6-dependent manner and impairs extravasation of basal-like breast cancer cells to the lungs." (PMID 29520340, 2018). "We further identified that the TP63 gene was repressed by this precision-guided machinery of TRPS1-CHD4/NuRD(MTA2) complex, which decommissions its enhancer leading to a decrease in ΔNp63 and enhancing the metastatic ability of breast cancer cells." (PMID 30563971, 2018). "TP63 has two subtypes, but which one responsible for breast cancer is not specified." (PMID 35480110, 2022). "Furthermore, it has been found that IRF6 (target of TP63) is induced by the NOTCH signaling pathway, which plays vital roles in the development and progression of cancers through regulating ZEB1 expression and EMT pathway, in breast cancer and keratinocytes." (PMID 33156825, 2020). "Also, breast cancer patients with high TRPS1 and low TP63 expression had better overall survival." (PMID 30563971, 2018).